PGR (progesterone receptor)
Diseases named in the same sentence as PGR in open-access papers (continued):
Sharing a sentence is not in itself a finding about the gene and the disease.
invasive ductal carcinoma (143 papers, 2005 to 2025). "One study revealed that TIMP3, which is frequently hypermethylated in infiltrating ductal carcinomas, is associated with increased tumor grade and nodal metastasis, along with increased expression of ER, progesterone receptor (PR), and Her2." (PMID 38069080, 2023). "Indeed, it was shown that activation of PPARδ in the mouse mammary epithelium results in the appearance of estrogen receptor- and progesterone receptor-positive and ErbB2-negative infiltrating ductal carcinomas which are associated with an up-regulation of Plac1." (PMID 24304549, 2013). "Invasive ductal carcinoma was the predominant histology (n=275; 91.9%), with estrogen receptor and progesterone receptor positivity observed in 185 (61.9%) and 179 (59.9%) patients, respectively." (PMID 40984893, 2025). "The first tumor, an invasive ductal carcinoma (G1), was estrogen and progesterone receptor-positive and HER2-negative, with a low proliferative index (Ki67 10%)." (PMID 40926949, 2025). "Pathological analysis of the surgical specimen confirmed invasive ductal carcinoma (estrogen receptor [ER]: 95%, progesterone receptor [PgR]: 85%, HER2: 2+ [fluorescence in situ hybridization, FISH negative]), with macrometastasis in one sentinel lymph node." (PMID 40761476, 2025). "A core needle biopsy revealed an invasive ductal carcinoma that was estrogen receptor (ER) positive, progesterone receptor (PR) positive, and human epidermal receptor 2 (HER2) negative." (PMID 39974553, 2025). "It exhibits poor outcomes andsuboptimal responses to systemic chemotherapy compared with standard invasive ductal carcinomas.MBC is typically triple-negative and deficient in the expression of HER2, progesterone receptor (PR) and the estrogen receptor (ER)." (PMID 40230896, 2024). "Pathology revealed a poorly differentiated infiltrating ductal carcinoma, estrogen receptor positive (ER+) 100%, progesterone receptor positive (PR+) 95%, and human epidermal growth factor receptor-2 (HER2) negative." (PMID 38912178, 2024). "The pathological diagnosis was invasive ductal carcinoma, nuclear grade 1, ER+ (J score 3b), PgR+ (J score 3a), HER2- (score 1+), with a Ki67-labeling index of less than 5%." (PMID 39371746, 2024). "Biopsies confirmed a poorly differentiated, infiltrating ductal carcinoma that was estrogen and progesterone receptor positive and human epidermal growth factor receptor-2 negative." (PMID 38912178, 2024). "The median age of the patients was 52.5 (range from 36 to 75) years, and 17 (85%) of them were diagnosed with invasive ductal carcinoma and all patients exhibited progesterone receptor-positive tumors." (PMID 38459836, 2024). "Biopsy showed invasive ductal carcinoma of the left breast (estrogen receptor [ER]/progesterone receptor positive [PR], human epidermal growth factor receptor-2 [HER2] negative) and ductal carcinoma in situ of the right breast (ER/PR positive)." (PMID 37397657, 2023). "Most patients (83%) had invasive ductal carcinoma; half had a primary tumor >20 mm in size (pT2); 27% had grade 3 tumors, 90% a Ki67 level >20%, and 40% a PgR expression ≤20%." (PMID 37291235, 2023). "IDC: Invasive ductal carcinoma; MC: Mixed carcinoma; ER: Estrogen receptor; PgR: Progesterone receptor; HER2: Human epidermal growth factor receptor 2; NPI: Nottingham prognostic index; Ref: Reference; P*: Fisher’s exact test." (PMID 38022007, 2023). "The tumor was classified as invasive ductal carcinoma, estrogen receptor (ER) positive, progesterone receptor (PgR) positive, and HER2 positive." (PMID 37361653, 2023). "We report the case of a 63-year-old female with a history of estrogen and progesterone receptor positive invasive ductal carcinoma with osseous metastases to the ribs and skull, major depressive disorder, and unspecified anxiety." (PMID 36002899, 2022).
invasive ductal carcinoma (continued). "A pathological examination revealed the following: invasive ductal carcinoma, pT2 (22 mm), nuclear grade 3, pN0, estrogen receptor (ER) and progesterone receptor (PgR) positive, human epidermal growth factor receptor 2 (HER2) negative, and pT2N0M0 stage IIa." (PMID 35980544, 2022). "Patient 1 was diagnosed at the age of 29 years with an invasive ductal carcinoma of her left breast (stage pT2N0M0; G2, ER 90%, PgR 1%)." (PMID 34072463, 2021). "A total of 26,339 ER/PgR-positive subjects diagnosed with invasive ductal carcinoma (IDC) or invasive lobular carcinoma (ILC) were analyzed." (PMID 34638491, 2021). "Mammography and biopsy of the breast mass identified estrogen receptor/progesterone receptor-positive invasive ductal carcinoma, consistent with the bone marrow biopsy, confirming the diagnosis of metastatic breast cancer." (PMID 34336518, 2021). "The invasive ductal carcinoma was estrogen receptor (ER) positive (90%), progesterone receptor (PR) positive (60%), and human epidermal growth factor receptor 2 (HER2) (1+); no metastatic lymph nodes were found." (PMID 31914067, 2020). "In the case lost to follow-up in February 2017, the patient was diagnosed during the postpartum period with invasive ductal carcinoma cT3N0 (ER−, PgR−, and HER2+) with liver, lung, and bone metastases." (PMID 33036248, 2020). "ER expression has been found in 50%-80% of cases and PgR expression is found in 60%-70% of cases of invasive ductal carcinoma." (PMID 32944466, 2020). "This patient was a 37-year-old multiparous woman with invasive ductal carcinoma G3, ER+, PgR+, HER2−, T4bN3M1 with skin metastases." (PMID 33036248, 2020). "According to western studies, ER expression has been found in 50%-80% of cases, and PgR expression is found in 60%-70% of cases of invasive ductal carcinoma." (PMID 32944466, 2020). "Histopathological examination revealed invasive ductal carcinoma, pT3N1M0 that was estrogen receptor (ER)- and progesterone receptor (PgR)-positive." (PMID 30771195, 2019). "The histopathological findings revealed invasive ductal carcinoma, pT3N1M0, which was estrogen receptor (ER)- and progesterone receptor (PgR)-positive." (PMID 30771195, 2019). "The histology of the vulvar tumor revealed an invasive ductal carcinoma of the breast, and immunohistochemical staining of the vulvar specimen showed the tumor cells to be 100% estrogen-receptor-positive and 100% progesterone-receptor-positive." (PMID 28510222, 2017). "Regarding the histological features, the majority were intermediate/moderate grade (40.8%), estrogen receptor-positive (74.6%), progesterone receptor-positive (63.1%), stage IV (4.9%) and with a diagnosis of invasive ductal carcinoma (78.4%)." (PMID 28341842, 2017). "At the age of 34, the patient developed an invasive ductal carcinoma of the right breast (G2, ER and PgR positive, p185 3 + at biopsy), that was treated by neoadjuvant chemotherapy with carboplatin and taxol." (PMID 26482194, 2015). "We identified subtypes of invasive ductal carcinoma of the breast by determining estrogen receptor, progesterone receptor and HER2 status." (PMID 24586742, 2014). "The majority of tumours were invasive ductal carcinomas (59 patients, 79.7%) and scored as grade 3 (59.5%), 32 patients had an ER-positive tumour (43.2%), 20 patients had a PgR-positive tumour (27.0%) and 35 had an ER and/or PgR-positive tumour (47.3%)." (PMID 22842582, 2012). "Mammography of the left breast revealed a 15-mm lesion in the upper outer quadrant and on core biopsy it was shown to be a grade I invasive ductal carcinoma which was oestrogen and progesterone receptor positive." (PMID 18492251, 2008). "Pathological examination revealed invasive ductal carcinoma measuring 1.8 cm, which was estrogen receptor (ER)-positive, progesterone receptor (PR)-positive, human epidermal growth factor receptor type 2 (HER2)-unknown and negative for lymph node involvement." (PMID 40062053, 2025).
invasive ductal carcinoma (continued). "The most common clinicopathological characteristics of the patients were invasive ductal carcinoma (69.3%), clinical stage II (44.6%), estrogen receptor positivity (45.5%), progesterone receptor positivity (46.3%), HER2 receptor negativity (52.8%), and Luminal A molecular subtype (39%)." (PMID 38898118, 2024). "The ultrasound-guided breast biopsy revealed an infiltrating ductal carcinoma of grade 2 in the right breast, with estrogen receptor (ER) 90%, progesterone receptor (PgR) 90%, human epidermal growth factor receptor 2 (HER2) 2+, in situ hybridization not amplified, and a Ki 67 index of 28%." (PMID 39131728, 2024). "The histopathologic report showed invasive ductal carcinoma in all patients, estrogen or progesterone receptor positivity in 10 patients (71.42%), and HER2 positivity (9 patients showed HER2 3+ on immunohistochemistry while 5 patients showed HER2 2+ and FISH positiveness)." (PMID 37173973, 2023). "Furthermore, an enhanced expression of cyclin D1 was also observed in 67.5% of invasive ductal carcinoma cases, where it was strongly correlated with estrogen receptor (ER) and progesterone receptor (PR) expression." (PMID 33920506, 2021). "Ultrasound core-needle biopsy of the suspicious right breast mass confirmed invasive ductal carcinoma, nuclear grade 2, Ki67 index of 55%, estrogen receptor–positive (H score of 180), progesterone receptor–positive (H score of 135), HER2-positive (3+ on immunohistochemistry)." (PMID 29900024, 2017). "Furthermore, we analyzed the expression of E-cadherin and C/EBPβ in a series of eight invasive ductal breast carcinomas, which had been classified according to their status of estrogen receptor, progesterone receptor and HER2." (PMID 23955085, 2013). "On the right side, the first mass, an area of about 13-mm of micro calcification, was situated in the upper outer quadrant at the 10'o clock position, and on core biopsy was confirmed as a grade I invasive ductal carcinoma, also both oestrogen and progesterone receptor positive." (PMID 18492251, 2008). "His primary tumor was invasive ductal carcinoma with hormone receptor-positive, HER2-negative disease (ER+, PgR+, HER2-, Ki-67 46%) and progressive metastatic disease." (PMID 41441520, 2025). "This patient had been diagnosed with estrogen receptor (ER), progesterone receptor (PR), and HER-2+ invasive ductal carcinoma (ICD)." (PMID 38801637, 2024). "HER2 is overexpressed in 80–90%; ER and PgR are positive in approximately 40% and 30%, respectively, in Paget’s disease, in contrast with 15–30% positive for HER2 in invasive ductal carcinoma." (PMID 32770432, 2020). "The initial biopsy revealed invasive ductal carcinoma (IDC), and it was estrogen (ER) and progesterone receptor (PR) positive and human epidermal growth factor receptor 2 (HER2) negative." (PMID 32884827, 2020). "A pathological examination revealed an estrogen receptor-positive (ER-positive), progesterone receptor-positive (PgR-positive), and human epidermal growth factor receptor 2-positive (HER2-positive) invasive ductal carcinoma." (PMID 29987656, 2018). "Pathologically, all cases were invasive ductal carcinoma (IDC) and estrogen receptor (ER) positive, 97.8% were progesterone receptor (PR) positive and 24.5% had human epidermal growth factor receptor 2 (HER2) over-expression." (PMID 29203780, 2017). "One thousand one hundred eighty consecutive patients with invasive ductal breast carcinoma were included and distributed in 16 subgroups (four HER2 phenotypes (0+, 1+, 2+ and 3+) times four ER/PgR phenotypes)." (PMID 28356061, 2017).
invasive ductal carcinoma (continued). "He had an invasive ductal carcinoma, stage II, lymph node positive, HER2– and ER+/PgR+, and low Ki-67 levels." (PMID 27377827, 2016). "MBC was an invasive ductal carcinoma in all cases, stage I (3 cases) and III (2 cases); all cases were ER+/PgR+, with high levels of Ki67, and only 1 was HER2+." (PMID 27377827, 2016). "She subsequently underwent a nipple-sparing mastectomy, with pathology indicating a triple-negative invasive ductal carcinoma (estrogen receptor, progesterone receptor, and human epidermal growth factor receptor 2 all negative)." (PMID 41107501, 2025). "Invasive ductal carcinoma in two patients was positive for estrogen receptor and negative for HER2, while invasive ductal carcinoma in the other patient was triple-negative for estrogen receptor, progesterone receptor, and HER2 with a high Ki-67 index." (PMID 40470417, 2025). "Three months after remission, she developed stiffness in the contralateral breast, and biopsy revealed grade 3 invasive ductal carcinoma that was estrogen receptor (ER)-positive, progesterone receptor (PR)-negative, and HER2 (1+)." (PMID 40669200, 2025). "Biopsy of the breast mass resulted in pathology revealing infiltrating ductal carcinoma of the right breast with estrogen receptor (ER), progesterone receptor (PR), and HER2 receptor negative (triple negative)." (PMID 39958080, 2025). "At surgery, an infiltrative ductal carcinoma was diagnosed (receptor arrangement: ER 95%; PgR 90%; Ki-67 23%; Her 2 negative; grading G2) with positive histological evaluation of the axillary lymph node for BC metastases." (PMID 38201413, 2024). "A second US-guided biopsy was then suggested, and G3, ER-negative, PgR-negative, Ki67 = 75%, c-erb-2-positive (3+) invasive ductal carcinoma was confirmed." (PMID 38785498, 2024). "At surgery, an infiltrative ductal carcinoma was diagnosed (receptor arrangement: ER: 95%; PgR 30%; Her 2 negative; Ki-67%: 40%; grading G3)." (PMID 38201413, 2024). "At surgery, an infiltrating ductal carcinoma was diagnosed (receptor arrangement: ER: 90%; PgR: 90%; Ki-67: 25%; Her 2 negative; grading G3)." (PMID 38201413, 2024). "At surgery, an infiltrative ductal carcinoma was diagnosed (receptor arrangement: ER: 80%; PgR: 60%; Ki-67: 35%; Her 2 negative; grading G2)." (PMID 38201413, 2024). "The pathological diagnosis was invasive ductal carcinoma, histological grade 2, estrogen receptor (ER) negative, progesterone receptor (PgR) negative, and human epidermal receptor 2 (HER2) negative (score 1+)." (PMID 39371746, 2024). "At surgery, an infiltrative ductal carcinoma was diagnosed (receptor pattern ER 95%; PgR 95%; Ki-67: 25%; Her 2 negative; grading G3)." (PMID 38201413, 2024). "Final pathological examination showed invasive ductal carcinoma with 86% of cancerous cells expressing ER, 78% PgR, 16% Ki-67, but not HER2." (PMID 36248976, 2022). "She underwent Tru-cut biopsy with a diagnosis of invasive ductal breast carcinoma (95% of tumor cells expressed estrogen receptor (ER), 40% progesterone receptor (PgR), 40% Ki67 and were HER2 negative)." (PMID 36248976, 2022). "The breast biopsy specimen from left mammary nodule confirmed infiltrating ductal carcinoma, grade 2, Estrogen Receptor (ER)-positive (30%), Progesterone Receptor (PR)-negative, HER2-positive (2+ by IHC and FISH positive) and Ki67 22%." (PMID 34073827, 2021). "PR, progesterone receptor; IDC, invasive ductal carcinoma; ILC, invasive lobular carcinoma." (PMID 33252186, 2021). "Ultrasound guided biopsy revealed a grade III, lymph-node positive invasive ductal carcinoma, 10 cm, noted to be estrogen receptor/progesterone receptor (ER/PR) negative and human epidermal growth factor receptor 2 (HER2) positive." (PMID 33704190, 2020).
invasive ductal carcinoma (continued). "The postoperative pathological diagnosis was invasive ductal carcinoma, grade II, stage I. The sample was positive for estrogen receptor and progesterone receptor and negative for cerbB-2." (PMID 32846803, 2020). "All four tumors were infiltrating ductal carcinomas and three of the tumors were estrogen receptor-negative, progesterone receptor-negative, and human epidermal growth factor receptor 2-negative (triple-negative)." (PMID 32455662, 2020). "All PBCs were invasive ductal carcinomas, the pathological grade was high (grade 2–3), 29% of tumors were estrogen receptor (ER)-negative, 50% were progesterone receptor (PR)-negative, and 21% were ERBB2-positive." (PMID 31086113, 2019). "The histopathological examination revealed invasive ductal carcinoma, pT1N0M0, which was negative for ER, PgR, and human epidermal growth factor receptor 2 (HER2)." (PMID 30771195, 2019). "The Low-B patient was a 65-year-old HER2 0 group woman with a 16 × 15 mm lesion of the scirrhous subtype of invasive ductal carcinoma, no lymph node metastasis and immunohistochemistry staining showing 90% ER, 80% PgR, and 5% Ki-67." (PMID 29204848, 2018). "The majority of male breast tumors were invasive ductal carcinomas (85.9%), estrogen receptor positive (ER+, 94.2%), progesterone receptor positive (PR+ 88.4%), and HER2 negative (79.2%)." (PMID 30564557, 2018). "The High-B patient was a 67-year-old HER2 1 + group woman, with a 15 × 15 mm lesion of the papillotubular subtype of invasive ductal carcinoma, no lymph node metastasis, and immunohistochemistry staining also showing 90% ER, 80% PgR, and 5% Ki-67." (PMID 29204848, 2018). "Biopsy specimen by core needle biopsy from the left breast lump showed an invasive ductal carcinoma that was both estrogen receptor (ER)- and progesterone receptor (PgR)-negative with a HER2 of 3+ by immunohistochemistry assay." (PMID 28220470, 2017). "The histology was poorly differentiated invasive ductal carcinoma (estrogen and progesterone receptor negative, HER2 positive) and the patient was negative for germline BRCA 1 and 2 mutations." (PMID 28856077, 2017). "Pathological evaluation confirmed residual invasive ductal carcinoma within the breast tissue (ER- and PgR-negative, HER2 3+) and metastatic carcinoma within three dissected axillary lymph nodes." (PMID 28220470, 2017). "Patient P6, at the age of 35 years, developed an infiltrating ductal carcinoma of the right breast, which was estrogen receptor-positive, progesterone receptor-negative and Her2/neu 3+, with loco-regional lymph node metastasis." (PMID 25683334, 2015). "A 62-year-old lady, previously healthy, was treated with adjuvant therapy for left breast stage II, high grade invasive ductal carcinoma which was node negative, oestrogen receptor negative, progesterone receptor positive, and HER2 receptor positive." (PMID 26605100, 2015). "Clinically, the majority of these tumors are invasive ductal carcinomas with a triple negative phenotype (lacking the estrogen receptor (ER) and progesterone receptor (PR), and do not overexpress the growth factor receptor Her2)." (PMID 24637461, 2014). "Biopsy of the 9 o'clock breast lesion showed invasive ductal carcinoma, positive for estrogen receptor (ER, 100%) and progesterone receptor (PR, 24%) and negative for HER2 overexpression." (PMID 25364575, 2014). "This truncating mutation was found in a Chinese woman who developed invasive ductal carcinoma at age 38, which was negative for the expression of the estrogen- and HER-2 receptors and positive for the expression of the progesterone-receptor." (PMID 23977390, 2013). "She had previously undergone a left modified radical mastectomy followed by 8 courses of CMF chemotherapy and tamoxifen treatment for 3 years, for an estrogen receptor (ER) (+++)-positive, progesterone receptor (PR) (+++)-positive, T1N0M0 invasive ductal breast carcinoma." (PMID 23761829, 2013).